PGLYRP1 (peptidoglycan recognition protein 1)
Diseases named in the same sentence as PGLYRP1 in open-access papers (continued):
Sharing a sentence is not in itself a finding about the gene and the disease.
tumor (continued). "Interestingly, PGLYRP1 expression was detected in 26.19% of samples with poor or undifferentiated histological tumour differentiation (grade 3–4) and in 11.94% with well to moderate differentiation (grade 1–2)." (PMID 38754953, 2024). "Concerning metastatic capacity, PGLYRP1 KO in both cell lines significantly reduced the number of tail micrometastases, supporting the hypothesis that PGLYRP1 has a role in tumour formation and metastasis." (PMID 38754953, 2024). "Indeed, PGLYRP1 overexpression protected cells from immune-mediated cytotoxic effects, and its knockout (KO) impeded tumour growth in immunocompetent mice." (PMID 38754953, 2024). "While more studies are required, PGLYRP1 certainly modulates the tumour immune cell composition and may play a previously unrecognised role in altering immune cell behaviour, promoting their protumoural characteristics and influencing their survival." (PMID 38754953, 2024). "PGLYRP1 interacts with Hsp70 to induces cytotoxic activity in tumor cells via TNFR1 receptor." (PMID 29915691, 2018). "Also, through its interaction with Hsp70 on cytotoxic lymphocytes, PGLYRP1 possesses anti-tumor cell activity." (PMID 23844029, 2013). "Additionally, PGLYRP1 can form a stable complex with heat shock protein 70 (Hsp70), called the Tag7-Hsp70 complex, which exhibits cytotoxic effects on tumour cells by inducing programmed cell death pathways, including apoptosis and necroptosis, via TNFR1 receptor signalling." (PMID 41487016, 2026). "Consequently, the grade 3–4 samples, associated with aggressive tumour behaviour, presented higher levels of PGLYRP1 than grade 1–2 samples, although it was not significant probably due to the limited number of samples." (PMID 38754953, 2024). "On the other hand, PGLYRP1 is pro-inflammatory alone, but in combination with HSP70 of the CMEs, it becomes cytotoxic to tumor cells." (PMID 39204415, 2024). "Here, we now present a novel role for PGLYRP1 as a critical contributor of CSC immune evasion in murine and human tumours." (PMID 38754953, 2024). "We have found that the Tag7 protein (PGLYRP1) is a ligand of the TNFR1 proinflammatory receptor present on the surface of many cells, including immune and tumor cells." (PMID 37511122, 2023). "In contrast, LL-37, ARG1, PGLYRP1 and S100A12 also exhibit antitumor activity affecting tumor cells directly or through the modulation of specific immune and nonimmune stromal cell populations." (PMID 36230605, 2022). "We have shown previously that the innate immunity protein Tag7 (PGLYRP1), recently described as a ligand for TREM-1, also induces activation of cytotoxic lymphocytes that kill MHC-negative tumor cells." (PMID 34206968, 2021). "This study provides a detailed analysis of the effect of Tag7 (PGRP-S, PGLYRP1) on the development of lymphocyte subpopulations cytotoxic against MHC-negative tumor cells in a pool of peripheral blood mononuclear cells (PBMCs)." (PMID 33291689, 2020). "Thus, we analysed a scRNA-seq dataset obtained from primary tumours of patients with PDAC41 and found that PGLYRP1 was expressed in few cells, mainly in the tumour compartment." (PMID 38754953, 2024). "To investigate the potential influence of the immune system and further study the possible role of PGLYRP1 in PDAC stemness, we performed an additional tumour formation assay in immunodeficient NOD.CB17-Prkdcscid/scid/Rj (NOD.SCID) mice injecting 103 cells, the limiting dilution obtained above." (PMID 38754953, 2024). "However, there were no significant changes in MΦs, CD206+ MΦs, general T cells, and CD4+ and CD8+ T-cell subsets in OE tumours, indicating that PGLYRP1 does not likely influence the infiltration or retention of these immune subsets." (PMID 38754953, 2024). "In PGLYRP1 KO cell-injected pancreata (in which tumours did not form), we could only evaluate the immune cells that remained after tumour cell clearance, which we compared against the pancreata of control mice." (PMID 38754953, 2024).
cancer (9 papers, 2013 to 2025). A tumor composed of atypical neoplastic, often pleomorphic cells that invade other tissues. "Taken together, LTF, ARG1, PGLYRP1, S100A12 and CAMP/LL-37 affect the human immune system at various levels by producing both protumorigenic and anticancer effects in a tissue- and cancer-specific manner." (PMID 36230605, 2022). "From these data, we selected potential biomarkers of cancer including six upregulated proteins (RNF213, CTSG, PGLYRP1, RPL8, S100A8, S100A9) and two downregulated proteins (GPX1, TNS1)." (PMID 34361002, 2021). "Six of these proteins had a higher abundance in cancer patients than in healthy controls (RNF213/ring finger protein 213; CTSG/cathepsin G; PGLYRP1/peptidoglycan recognition protein 1; RPL8/ribosomal protein L8; S100A8/S100 calcium binding protein A8; S100A9/S100 calcium binding protein A9)." (PMID 34361002, 2021).
kidney disease (2 papers, 2020 to 2025). "Renin, GDF15, PRSS8, RARRES2, PGLYRP1, LOX1, and UPAR, all robustly related to PA, have been related to cardiovascular or kidney disease via different pathways." (PMID 40498722, 2025).
PGLYRP1 also shares sentences with these, for which no sentence is quoted: immune deficiency (13 papers); E. coli infection (5); fungal infection (4); viral infection (4); autoimmune disease (3); cardiovascular disease (3); contact dermatitis (3); Crohn disease (3); gram-negative bacterial infections (3); gram-positive bacterial infections (3); Anxiety (2); atopic dermatitis (2); breast tumor (2); COVID-19 (2); diabetes (2); immune diseases (2); Listeria infection (2); parasite (2); parasite infection (2); psoriasis (2); adenoma (1); alopecia areata (1); bipolar disorder (1); chronic kidney disease (1); co-infection (1); colorectal cancer (1); Cryptococcal meningitis (1); dental caries (1); Drosophila C virus infection (1); food allergy (1).
A further 20 diseases each share a sentence with PGLYRP1 in 1 paper.